ZNF536 (zinc finger protein 536)
Description:
Transcriptional repressor that negatively regulates neuron differentiation by repressing retinoic acid-induced gene transcription. Binds and interrupts RARA from binding to retinoic acid response elements (RARE) composed of tandem 5'-AGGTCA-3' sites known as DR1-DR5. Recognizes and binds 2 copies of the core DNA sequence 5'-CCCCCA-3'.
Synonyms: KIAA0390
Tractability: PROTAC: ubiquitination databases record sites on it; its protein half-life has been measured.
Gene: Protein-coding gene on chromosome 19 (30,224,891 to 30,713,586, forward strand). Ensembl gene ENSG00000198597.
Subcellular location: Nucleus
Subcellular location (Human Protein Atlas): Cell Junctions; Nucleoplasm
Gene Ontology:
Molecular function: DNA-binding transcription repressor activity, RNA polymerase II-specific; RNA polymerase II cis-regulatory region sequence-specific DNA binding; DNA-binding transcription factor activity, RNA polymerase II-specific; retinoic acid-responsive element binding
Biological process: negative regulation of transcription by RNA polymerase II; regulation of DNA-templated transcription
Cellular component: nucleus
Genetic constraint (gnomAD): Loss-of-function variants: 13 observed, 84.21 expected, observed/expected ratio (o/e) 0.15, 90% interval 0.1 to 0.25. The upper end of that interval is the gene's LOEUF score, 0.25, which puts it in group 1 of 6, group 1 being the genes least tolerant of losing a copy. Missense variants: 1,536 observed, 1,773.4 expected, observed/expected ratio (o/e) 0.87, 90% interval 0.83 to 0.9. Synonymous variants: 811 observed, 758.59 expected, observed/expected ratio (o/e) 1.07, 90% interval 1.01 to 1.13.
Homologues: Orthologues: chimpanzee ZNF536 (99% identical), macaque ZNF536 (99% identical), pig ZNF536 (92% identical), dog ZNF536 (91% identical), mouse Zfp536 (89% identical), rat Zfp536 (89% identical), rabbit ZNF536 (88% identical), guinea pig ZNF536 (86% identical), tropical clawed frog znf536 (71% identical), zebrafish znf536 (61% identical). Paralogues in human: ZNF516 (22% identical), ZNF219 (20% identical), ZNF217 (18% identical), SALL3 (14% identical), SALL1 (14% identical), SALL4 (11% identical), HIVEP2 (11% identical), HIVEP1 (11% identical), HIVEP3 (11% identical), BCL11B (10% identical), BCL11A (9% identical), RREB1 (9% identical), and 2 more.
Diseases named in the same sentence as ZNF536 in open-access papers:
ZNF536 is named in the same sentence as 24 diseases in open-access papers, as found by Europe PMC text mining. Sharing a sentence is not in itself a finding about the gene and the disease. The quoted sentences say what the papers report.
schizophrenia (6 papers, 2018 to 2025). A major psychotic disorder characterized by abnormalities in the perception or expression of reality. "ZNF536, a brain-specific transcriptional repressor, has recently emerged as a candidate risk gene for schizophrenia (SZ), yet its functional role in human neurodevelopment remains poorly understood." (PMID 41163642, 2025). "Genetic variants in ZNF536 contribute to the risk for neuropsychiatric disorders such as schizophrenia, autism, and others." (PMID 38331943, 2024). "Genomic studies have implicated the gene ZNF536 as a candidate risk factor for neuropsychiatric disorders, particularly schizophrenia." (PMID 38331943, 2024). "In chromosome 19, the lead SNP (rs28567442; P = 6.31 × 10−10) is embedded in ZNF536, implicated in the development of the forebrain, and associated with schizophrenia." (PMID 38811692, 2024). "Genomic studies have implicated ZNF536 in neuropsychiatric disorders, particularly schizophrenia." (PMID 38331943, 2024). "Besides NRG1 rs6994992, 10 other schizophrenia risk variants were also investigated in this study and the results showed that only ZNF536 rs2053079 was nominally associated with creativity." (PMID 31649580, 2019). "Zinc-Finger 536 (ZNF536) was identified as a candidate schizophrenia gene and a double-knockout zebrafish line shows behavioral and neuroanatomical (decreased forebrain volume) changes." (PMID 34035472, 2021). "Based on this evidence, it is possible that ZNF536 rs2053079 may play a role in the relationship between schizophrenia and creativity." (PMID 31649580, 2019). "For other schizophrenia risk variants, the result only demonstrated a nominal association between ZNF536 rs2053079 and creativity measures which would not survive correction for multiple testing." (PMID 31649580, 2019). "Because ZNF536 rs2053079 has not been previously examined for its association with creativity, our result provides the first evidence for the association of this schizophrenia risk variant with creativity in healthy subjects." (PMID 31649580, 2019).
bipolar disorder (2 papers, 2014 to 2018). A disorder of the brain that causes unusual shifts in mood, energy, activity levels and the ability to carry out day-to-day tasks. "The NCALD and ZNF536 genes have been shown to be linked with bipolar disorder." (PMID 30034349, 2018). "The PREX1 and ZNF536 genes have been shown to be associated with MDD and bipolar disorder, respectively." (PMID 30034349, 2018). "Comparison with other published GWA studies for bipolar disorder, excluding those with partial overlap of subjects, appears to corroborate several loci and candidate genes, including CNTNAP5, ZNF804A, ZNF659, SORCS2, and ZNF536." (PMID 24387768, 2014).
breast carcinoma (2 papers, 2012 to 2023). "Experimental siRNA silencing of ZNF536 in breast cancer cell lines harboring 19q12 amplification has shown reduced cell viability compared to breast cancer cell lines lacking the amplification." (PMID 37046633, 2023). "Silencing of CCNE1, PLEKHF1, POP4, ZNF536 and TSHZ3 expression selectively reduced cell viability in cancer cells harbouring 19q12 gene amplification but had a significantly lower impact on the survival of breast cancer cells lacking amplification of this locus (t-test P < 0.05)." (PMID 22433433, 2012).
glioma (2 papers, 2024 to 2025). A benign or malignant brain and spinal cord tumor that arises from glial cells (astrocytes, oligodendrocytes, ependymal cells). "GEPIA2 exhibited that ZNF536 was predominantly expressed in glioma and pheochromocytoma and paraganglioma, and the two main isoforms (ENST00000355537.3 and ENST00000592773.2) showed a similar expression pattern." (PMID 38720348, 2024).
lung adenocarcinoma (2 papers, 2022 to 2024). A carcinoma that arises from the lung and is characterized by the presence of malignant glandular epithelial cells. "For lung cancer, ZNF536 mutation was associated with longer survival in primary lung adenocarcinoma (LUAD), but its prognosis was poor in metastatic LUAD and SCLC." (PMID 38720348, 2024). "ZNF536 has been found to play a critical part in the development of lung adenocarcinoma by promoting the migration and invasion of tumor cells." (PMID 36011407, 2022).
autism (1 paper, 2024). Persistent deficits in social interaction and communication and interaction as well as a markedly restricted repertoire of activity and interest as well as repetitive patterns of behavior. "The novel tank diving assay also revealed anxiolytic activity in znf536 KO zebrafish, similar to a knockout of the dyrk1aa ortholog of the DYRK1A autism risk gene." (PMID 38331943, 2024).
cervical squamous cell carcinoma (1 paper, 2024). A squamous cell carcinoma arising from the cervical epithelium. "Interestingly, despite the differences in ZNF536 mutation and copy number alterations, COAD and cervical squamous cell carcinoma exhibited similar pathway activities." (PMID 38720348, 2024).
esophageal tumor (1 paper, 2021). "For example, genomic regions near ZNF536 were hyper-accessible in HET-1A cells but less-accessible in both ESCC cell lines, which aligns with observation of significantly lower ZNF536 expression in human esophageal tumor tissues." (PMID 34722266, 2021).
liposarcoma (1 paper, 2018). A usually painless malignant tumor that arises from adipose tissue. "In our study we also noted deleterious mutations in 7 other genes (CTNNB1 (R151H), MECOM (R208C), ZNF536 (T688M), EML4 (W729L), CSMD3 (P627S), PBRM1 (N639K), PPP1R3A (C788Y)) that have also not been described previously in WD/DD liposarcoma." (PMID 29731991, 2018).
lung carcinoma (1 paper, 2024). "In conclusion, this study provides an integrative analysis of the role of ZNF536 in cancer, with a specific focus on lung cancer." (PMID 38720348, 2024). "The RNA expression of ZNF536 was extremely low in lung cancer cell lines, so we constructed one of these lines with overexpressed ZNF536." (PMID 38720348, 2024). "Finally, SCLC lung cancer cell lines were used to study the potential regulation of ZNF536." (PMID 38720348, 2024).
neuroblastoma (1 paper, 2025). Neuroblastoma (NB) is the most common solid, extracranial childhood tumor. "Using CRISPR knockouts in SH-SY5Y neuroblastoma cells, we mapped allele-specific effects of loss of ZNF536 on retinoic acid–induced neuronal differentiation." (PMID 41163642, 2025). "Although ZNF536 might function as a safeguard against early differentiation in stem-like contexts, our data indicate that in an even more committed state such as neuroblastoma ZNF536 activity is additionally relevant to ordered programs of RA." (PMID 41163642, 2025).
neuroendocrine tumors (1 paper, 2024). "Considering that the methylation of ZNF536 was involved in the synaptic pathway associated with neuroendocrine neoplasms, demonstrating both diagnostic and prognostic value." (PMID 38720348, 2024). "Methylated ZNF536 were positively correlated with synaptic pathway related to neuroendocrine tumors." (PMID 38720348, 2024).
non-small cell lung carcinoma (1 paper, 2024). A group of at least three distinct histological types of lung cancer, including non-small cell squamous cell carcinoma, adenocarcinoma, and large cell carcinoma. "The ICGC pan-cancer profile revealed that ZNF536 mutations and copy number alterations could occur in the same sample, with the highest frequency observed in non-small cell lung cancer." (PMID 38720348, 2024).
Obesity (1 paper, 2024). Accumulation of substantial excess body fat. "Transcription factor ZFP536 (zinc finger protein 536) is involved in neurone differentiation and was associated with both Attention-Deficit/Hyperactivity Disorder (ADHD) and excessive body weight, linking psychological disorders with obesity." (PMID 38483771, 2024).
serous ovarian tumors (1 paper, 2010). "By interrogating data obtained from an earlier study we found ZNF536 expression to be low or absent in primary serous ovarian tumors, which may explain an unobservable reduction in gene expression (data not shown)." (PMID 21103391, 2010).
small cell lung carcinoma (1 paper, 2025). Small cell lung cancer (SCLC) is a highly aggressive malignant neoplasm, accounting for 10-15% of lung cancer cases, characterized byrapid growth, and early metastasis. "ZNF536 mutation is linked to a longer survival in LUAD but a worse prognosis in small-cell lung cancer and metastatic LUAD." (PMID 40686517, 2025).
uterine carcinosarcoma (1 paper, 2024). A usually aggressive malignant neoplasm arising from the uterine corpus and less often the cervix. "For example, uterine carcinosarcoma (UCS) showed a higher frequency of ZNF536 copy number alterations." (PMID 38720348, 2024).
cancer (6 papers, 2012 to 2024). A tumor composed of atypical neoplastic, often pleomorphic cells that invade other tissues. "Our results showed that ZNF536 alterations in cancer, including variations in copy number, mutation, and methylation." (PMID 38720348, 2024). "We found that the copy number alteration of ZNF536 was more concentrated in specific cancers compared to mutation." (PMID 38720348, 2024). "Similar to the previous study, ZNF536 mutation exhibited favorable prognostic value in the Canadian pan-cancer cohort primarily treated with PD-1 blockade." (PMID 38720348, 2024). "Importantly, ZNF536 mutation and amplification had opposite prognoses in Stand Up To Cancer-Mark Foundation (SU2C-MARK) LUAD cohort." (PMID 38720348, 2024). "We aimed to characterize the cancer driver genes, and found previous studies of ZNF536 to be misleading." (PMID 38720348, 2024). "This is the first study to characterize the role of ZNF536 in cancer, and our findings regarding its prognostic value, multi-omics analysis, cellular mapping, and immune infiltration regulation are insightful." (PMID 38720348, 2024). "To explore the alterations of ZNF536 across different cancer types, we utilized the cBioportal website for a pan-cancer analysis." (PMID 38720348, 2024). "In contrast, we uncovers the cancer types preferentially validated by ZNF536 (e.g., OV, LUAD and SCLC), and explored potential targets." (PMID 38720348, 2024). "Part zinc finger RNAs in cancer exhibit lineage-specific patterns, while DNA methylation is more readily quantified dynamically and provides the genome information, with ZNF536 serving as an example." (PMID 38720348, 2024). "When grouped by ZNF536 expression, we found that in the cancer epithelium, ZNF536 exhibited co-expression with PHOX2B and AR, while being excluded from IFI27, IFI6, and ZFP36." (PMID 38720348, 2024). "However, the precise function of ZNF536, particularly in the context of cancer, remains largely uncharacterized." (PMID 38720348, 2024). "In ICGC pan-cancer data, ZNF536 alterations were identified in 9.8% of cases." (PMID 38720348, 2024). "Furthermore, the pan-cancer protein profile of ZNF536 remains to be characterized." (PMID 38720348, 2024). "Guided by the HTAN-SCLC cancer epithelium dataset, we further found that the RNA expression of ASCL1, PHOX2A and AR was regulated by ZNF536." (PMID 38720348, 2024). "Furthermore, analysis of the HTAN-SCLC dataset showed that ZNF536 was primarily expressed in the cancer epithelium and not in the ASCL1+ subpopulation." (PMID 38720348, 2024). "Targeting cancer epithelium is feasible, and we previously evaluated the anti-proliferation effect of enzalutamide in lung squamous carcinoma cell lines, but still have not investigated ZNF536 regulation of AR signaling pathway." (PMID 38720348, 2024). "For more than half of the MES and ADRN TFs (e.g., SIX1, MEOX1, and ZNF536), decreased cumulative survival was observed for two cancer types in particular; KIRP and UCEC, but to a lower extent in other cancers, indicating the influence of these TFs on patient survival in these cancers." (PMID 35201514, 2021).
tumor (5 papers, 2022 to 2024). "Combined with our previous work, mutant ZNF536 associated with total tumor mutational load (TMB) are promising markers for immune checkpoint inhibitor (ICI) therapies in LUAD." (PMID 38720348, 2024). "Our analysis highlighted three types of tumor subgroups: central memory and Th2 T-cell subgroups were downregulated by ZNF536 amplification." (PMID 38720348, 2024). "In addition, we analyzed the tumor mutation burden (TMB) in the TCGA cohort and found that, except for ZNF536 and FLG, the mutation frequency of the remaining genes with the highest mutation frequency was greater in the high-risk group." (PMID 39091494, 2024).
psychiatric disease (2 papers, 2024 to 2025). "These distinct enrichment patterns suggest that the genetic region of ZNF536 deleted in KI/del cells contains regulatory elements crucial for psychiatric disease-related gene expression." (PMID 41163642, 2025). "Collectively, these findings demonstrate that inactivation of ZNF536 via KI with frameshift primarily affects cellular metabolism and neurodegenerative pathways, while deletion of the ZNF536's region in compound heterozygous sample specifically disrupts psychiatric disorder-related gene networks." (PMID 41163642, 2025). "In psychiatric disorders, ZNF537/TSHZ3 and ZNF536 were expressed in the cerebral cortex, and supported by CRISPR information." (PMID 38720348, 2024).
neurodevelopmental disorder (1 paper, 2025). A behavioral and cognitive disorder with onset during the developmental period that involves impaired or aberrant development of intellectual, motor, or social functions. "Neuronal populations showed enriched expression of neurodevelopmental disorder-linked genes (NRXN3, CADM2, ZNF536) and synaptic signalling pathways." (PMID 41010342, 2025).
ZNF536 also shares sentences with these, for which no sentence is quoted: meningioma (1 paper); paraganglioma (1); pheochromocytoma (1).